FRG2C (FSHD region gene 2 family member C)
Tractability: No criterion of Open Targets' tractability assessment is met for any kind of drug.
Gene: Protein-coding gene on chromosome 3 (75,664,328 to 75,667,220, forward strand). Ensembl gene ENSG00000172969.
Subcellular location: Nucleus
Gene Ontology:
Cellular component: nucleus
Genetic constraint (gnomAD): Loss-of-function variants: 8 observed, 9.29 expected, observed/expected ratio (o/e) 0.86, 90% interval 0.5 to 1.53. That is too few expected variants to judge how well the gene tolerates losing a copy. Missense variants: 214 observed, 217.74 expected, observed/expected ratio (o/e) 0.98, 90% interval 0.88 to 1.1. Synonymous variants: 92 observed, 77.31 expected, observed/expected ratio (o/e) 1.19, 90% interval 1 to 1.41.
Homologues: Orthologues: chimpanzee FRG2C (99% identical), mouse Frg2f1 (27% identical). Paralogues in human: FRG2 (93% identical), FRG2B (93% identical).
Diseases named in the same sentence as FRG2C in open-access papers:
FRG2C is named in the same sentence as 1 disease in open-access papers, as found by Europe PMC text mining. Sharing a sentence is not in itself a finding about the gene and the disease. The quoted sentences say what the papers report.
esophageal squamous cell carcinoma (1 paper, 2025). Esophageal squamous cell carcinoma (ESCC) is a type of esophageal carcinoma (EC) that can affect any part of the esophagus, but is usually located in the upper or middle third. "FRG2C is a signature gene mutated in ESCC (esophageal squamous cell carcinoma) and proliferative verrucous leukoplakia (PVL)." (PMID 40563552, 2025).